JAK2 (Janus kinase 2)
Diseases named in the same sentence as JAK2 in open-access papers (continued):
Sharing a sentence is not in itself a finding about the gene and the disease.
breast cancer (continued). "However, we have reported that in human breast cancer cell lines Jak1 is also recruited in a Jak2-dependent manner for maximal PRL-activation of Stat5 and other signaling mediators." (PMID 23758962, 2013). "In summary, the prolactin-Jak2-Stat5 pathway, which may suppress breast cancer cell epithelial-to-mesenchymal transition, invasion and drug resistance, is potently and selectively suppressed by extracellular tumor acidosis." (PMID 24004716, 2013). "Furthermore, alternative mechanisms likely lead to loss of Nuc-pYStat5 in human breast cancer, such as inhibition of prolactin-Stat5 signaling by the tyrosine phosphatase PTP1B through inhibition of the Jak2 tyrosine kinase." (PMID 24004716, 2013). "It is thought that CypA might disrupt the F-actin structure in osteosarcoma cells or the regulation of JAK2 signaling in breast cancer cells and metastatic melanoma cell lines." (PMID 23031673, 2012). "Alternative but not mutually exclusive mechanisms recently reported include disruption of Stat5a/b phosphorylation during breast cancer progression through upregulation of the Jak2 tyrosine phosphatase, PTP1B, or inhibitory signaling to Stat5 by the truncated ERBB2 isoform, p100-t-ERBB2." (PMID 23036105, 2012). "As PRL mediates its effects via, among others, JAK2/STAT5 signaling in breast cancer cells, this could provide a means by which PRL could directly activate PPARα transcription independent from LKB1 and AMPK." (PMID 21294903, 2011). "NDRG2 overexpression in breast cancer (BC) significantly inhibited tumor cell growth by attenuating Janus tyrosine kinases (JAK2) and STAT3 pathways." (PMID 40378957, 2025). "Furthermore, Faecalibacterium prausnitzii is less abundant in breast cancer patients, which could suppress the growth of breast cancer cells through inhibition the JAK2/STAT3 signaling pathway." (PMID 40463381, 2025). "Moreover, we utilized the JAK2/STAT3-specific inhibitor WP1066 to determine whether activation of this pathway is essential for the CCT2-mediated progression of breast cancer cells." (PMID 39079960, 2024). "Therefore, in a case–control study nested in the NHS, we examined the association between circulating prolactin levels measured 10 or fewer years prior to diagnosis and risk of breast cancer by tumor expression of the PRLR, pSTAT5, and phosphorylated JAK2 (pJAK2)." (PMID 36882838, 2023). "In continuation of our research on the effects of inhibition of JAK2/STAT3 signaling pathway in breast cancer tumor cells, the aim of this study was to investigate whether CPT, naringenin, and their combination could modify immune response, immune cell proliferation, and cytokine production." (PMID 35606804, 2022). "Therefore, targeting Angiotensin initiation of NF-kB/IL-6/JAK2/STAT3 pathway could be a beneficial strategy in breast cancer therapies." (PMID 36431925, 2022). "Furthermore, it has been reported that LEP in breast cancer models, via JAK2/STAT3 pathway, promotes cell cycle progression by increasing the expression of cdk2 and cyclin D1 levels, thus inducing hyperphosphorylation and subsequent inactivation of the cell cycle inhibitor Rb." (PMID 36291602, 2022). "Furthermore, N-Ras appears to act via JAK2 to turn on IL8 expression in basal-like breast cancer." (PMID 36258226, 2022). "Although JAK2 mutations are absent in the majority of solid tumors, mounting evidences suggest that aberrant JAK2 signaling has an essential role in solid tumors such as colorectal cancer, breast cancer, lung cancer, prostate cancer, etc.." (PMID 30564118, 2018). "Ruxolitinib is an inhibitor of JAK1 and JAK2 that is approved to treat certain rare cancers of the blood and bone marrow, and there’s a good scientific evidence to think it might have anti-tumor effects against breast cancer as well." (PMID 29761158, 2018).
breast cancer (continued). "Thus our results reveal that chemoresistance in breast cancer is associated with activation of JAK/STAT signaling and suggest that JAK2 may be useful for combating chemoresistance in breast cancer." (PMID 29383118, 2017). "Additionally, JAK2/STAT3 activation has been linked to enhanced migration and invasion of breast cancer (BC) cells (Pathway D)." (PMID 40277814, 2025). "While PRL has been shown to regulate Hippo pathway leading to pigeon crop epithelial cell proliferation, our study showed that PRL/PRLR/Jak2 pathway results in Hippo pathway activation and nuclear exclusion of YAP in mammary epithelial and breast cancer cells." (PMID 40157909, 2025). "Analysis of catalytic-dead PTPRO mutant breast cancer cells confirmed that functional PTPRO is a determinant of the activation of the JAK2–YAP pathway and the suppression of breast cancer metastasis." (PMID 40016288, 2025). "To compare the anti-cancer effects of chalcone-9 with tamoxifen, an FDA-approved drug used for breast cancer treatment, and AG490, a selective JAK2 inhibitor frequently utilized in research, we evaluated their cytotoxic effects on breast cancer cells." (PMID 40199813, 2025). "In this study, we identified circRNA-14,052 as a novel oncogenic circRNA that promotes breast cancer progression by sponging miR-214-3p and upregulating IKBKB, thereby activating the IL-6/JAK2/STAT3 signaling axis." (PMID 41044672, 2025). "In the present study, the presence of the HPV16 E6 oncogene reduced the expression of JAK2 and STAT4, which are key regulators of the immune response and cell proliferation, potentially negatively impacting breast cancer prognosis." (PMID 40733498, 2025). "Silibinin downregulates the expression of the key migration regulators MMP-2 and MMP-9 through the Jak2/STAT3 and MEK/ERK pathways in breast cancer." (PMID 41470858, 2025). "This study uniquely explores Melittin’s interactions with JAK2, JAK3, and STAT3, which are crucial components of breast cancer signaling pathways." (PMID 40243485, 2025). "We treated breast cancer cell lines with the well-known tamoxifen, which has already been FDA-approved for breast cancer treatment, and AG490, which is used as a JAK2 selective inhibitor, to compare the cytotoxicity of chalcone-9." (PMID 40199813, 2025). "Both in vitro and in vivo data demonstrated that PTPRO inactivates the JAK2–YAP pathway and diminishes the metastatic ability of breast cancer." (PMID 40016288, 2025). "Bioinformatics analyses and subsequent assays of human breast cancer specimens revealed a reverse correlation between PTPRO expression and JAK2–YAP pathway activity." (PMID 40016288, 2025). "RT-qPCR results of a cross-sectional study showed that JAK2 wasdecreased and STAT3 elevated gene expression level in breast cancer; there was also a positive correlationbetween JAK2 and STAT3 expression." (PMID 40092547, 2025). "We also noted that African ancestry was associated with a higher frequency of copy number alterations in CD274/JAK2/PDCD1LG2 (n = 150; OR = 1.56; FDR = 0.01), which was preferentially found in ER/HER2-negative breast cancer." (PMID 41162424, 2025). "IL-6 expression is a critical step of breast cancer metastasis, leading to the activation of the JAK2/STAT3 signaling pathway that promotes proliferation, invasion, metastasis, and angiogenesis and inhibits apoptosis in breast cancers." (PMID 38673967, 2024). "Western blotting results showed that the expression levels of p-JAK2 and p-STAT3 in breast cancer cells were significantly decreased after PSP treatment." (PMID 38872110, 2024). "In summary, combining the previous studies with our study can enhance the persuasiveness of JAK2 and DAXX as candidate genes for breast cancer treatment." (PMID 39669558, 2024). "Inhibition of either CXCR4 or JAK2 suppresses STAT3 phosphorylation, reversing the proliferative and metastatic phenotypes of breast cancer." (PMID 38920657, 2024).
breast cancer (continued). "In breast cancer, this pathway is pivotal for the development of human CD44+CD24- stem cell-like cancer cells, and the inhibition of JAK2 prevents xenograft growth." (PMID 39079960, 2024). "This study demonstrated that GluOC facilitates the migration of MDA-MB-231 breast cancer cells through the ROCK1/MYPT1/MLC2 signalling pathway and promotes the proliferation of TNBC cells via the ROCK1/JAK2/PIK3CA/AKT signalling pathway." (PMID 39054484, 2024). "The results showed that JAK2, HPGDS, AR and PARP1 had good potential for targeted treatment of breast cancer." (PMID 38872110, 2024). "B6, for example, induced apoptosis in breast cancer cells by constitutively inhibiting STAT3 phosphorylation through allosteric interaction with JAK2, implying that JAK2 is essential for STAT3 activation." (PMID 38182570, 2024). "Previous studies have shown that JAK2 was overactive in triple-negative and HER-2 positive breast cancers." (PMID 38872110, 2024). "In this study, the core components regulate five key targets: MAPK1, LCK, JAK2, HSP90AA1, and EGFR, all of which are uniquely expressed in breast cancer." (PMID 39867914, 2024). "It is worth noting that the transcriptional expression levels of JAK2 and MAPK1 in breast cancer tissues differ from their protein expression levels." (PMID 39867914, 2024). "We previously demonstrated that CD44+CD24− cancer cells are enriched in basal-like tumors compared with other breast cancer subtypes and that CD44+CD24− cancer cells have heightened IL-6/JAK2/STAT3 signaling activity compared with other tumor cells." (PMID 38297352, 2024). "Further investigations reveal that the CXCL12/CXCR4 axis phosphorylates JAK2, thereby activating the STAT3 signaling pathway to promote breast cancer proliferation and metastasis." (PMID 38920657, 2024). "Accordingly, the role of JAK2 and LAMA3 in HER2+ breast cancer cells and their modulation by PGB-0-ol should be investigated further." (PMID 38028209, 2023). "In addition, we previously noted that TrkB activates the IL6/JAK2/STAT3 signaling pathway in breast cancer via the formation of the TrkB/JAK2 complex and then induces the EMT program by upregulating Twist-1, suggesting that DJ-1 and TrkB may orchestrate to activate the STAT3 signaling pathway." (PMID 37749450, 2023). "JAK2 and SRC have emerged as important therapeutic targets for several cancers including head and neck squamous cell carcinoma, breast cancer, lung cancer and gastric cancer." (PMID 37147297, 2023). "Tissue microarrays consisting of breast cancer specimens from a retrospective cohort (n = 850) were stained for IL6R, JAK1, JAK2 and STAT3 via immunohistochemistry." (PMID 37199043, 2023). "JAK-2, STAT3, and STAT5 regulate genes that promote breast cancer cell survival, proliferation, and metastasis." (PMID 36674719, 2023). "In breast cancer, miR-375 not only inhibits the stemness of breast cancer cells, but also reduces the adriamycin resistance of adriamycin resistant MCF-7Adr cells by impeding the JAK2/STAT3 signaling pathway." (PMID 35416122, 2022). "It was reported that the activation of IL-6/JAK2/STAT3 pathway promotes proliferation, invasion, metastasis and angiogenesis, and inhibits apoptosis in breast cancers." (PMID 36431925, 2022). "In an orthotopic allograft model incorporating breast cancer stem cell-enriched TNBC tumors, SL-145 potently suppressed tumor growth, angiogenesis, and metastases concomitant with dysregulation of the JAK2/STAT3 signaling pathway." (PMID 35501463, 2022). "Withaferin A activity has been found to modulate the JAK/STAT pathway in human breast cancer cells by decreasing phosphorylation of STAT3 and JAK2 in MDA-MB-231 breast cancer cell line." (PMID 36339589, 2022). "CPT acts like IL-12 and causes the release of perforin from CD4+ T cells through the phosphorylation of the JAK2/STAT4 pathway, mainly inhibited the growth of breast cancer cells." (PMID 36188552, 2022).
breast cancer (continued). "The results of our study revealed that CPT is capable of suppressing JAK2 and STAT3 phosphorylation in breast cancer cells and its combination with naringenin exerts as additive effect on JAK/STAT pathway." (PMID 35606804, 2022). "EGFR and HER2 dimerization modulated ACTA2 through the JAK2/STAT1 signaling pathway and ACTA2 gene abnormalities accelerated the invasion and metastasis of breast cancer cells." (PMID 34179721, 2021). "To further validate the result, we analyzed tissue specimens from HMUCC, and we found that EGFR, JAK2, and STAT3 were upregulated in breast-cancer tissues relative to the expression in normal tissues." (PMID 33446634, 2021). "Worth emphasizing is, JAK2 /STAT3 is a prerequisite for the maintenance and proliferation of CSC of breast cancer and developing of chemo- and radio-resistance." (PMID 33672756, 2021). "miRNA-101 was found to target different pathways that promote breast cancer cell apoptosis by inhibiting the expression of Jak2, EYA1 and SOX2 acting as a potential therapeutic target in breast cancer." (PMID 34200314, 2021). "The operation of TPH1-5-HT-5-HT7 axis utilized PI3K/Akt and JAK2/STAT3 signaling pathways that were activated through Gβγ components of the receptor, consistent with our previous findings in breast cancer cells." (PMID 34771469, 2021). "We concluded that breast cancer cells acquire resistance to IFN-γ and, thus, resistance to redirected lymphocytes, by downregulating JAK2." (PMID 33623012, 2021). "It was also demonstrated that induction of ACTA2 by EGFR and HER2 dimerization is regulated through a JAK2/STAT1 signaling pathway and that abnormal ACTA2 expression accelerates the invasiveness and metastasis of breast cancer cells." (PMID 34211976, 2021). "Aberrant JAK2/STAT3 signaling has been reported in various types of tumors, including breast cancer." (PMID 34120621, 2021). "It was reported that stem cell-like breast cancer cells showed high STAT3 activation and the JAK2/STAT3 signaling pathway is important in maintaining stem cell characteristics." (PMID 32326231, 2020). "According to previous studies, interleukin-6 (IL-6) can activate JAK2/STAT3 signaling, and repression of the IL-6/JAK2/STAT3 signaling axis has been reported to inhibit the migration, invasion, and tumor formation of breast cancer cells." (PMID 32503225, 2020). "Compelling experimental evidence from both clinical trials and animal studies demonstrated that the JAK2/STAT3 pathway plays a pivotal role in the initiation, progression, and metastasis of breast cancer." (PMID 32922496, 2020). "Gemini vitamin D analogue BXL0124 inhibits CD44-STAT3-mediated breast cancer invasion and metastasis by decreasing CD44 expression and STAT3 activation, as well as preventing CD44 binding to JAK2 and STAT3 in the cytoplasm." (PMID 33335857, 2020). "Re-expression of the receptor was also discussed and shown to have a tumour-suppressive function in the mammary cancer cell line MDA-MB-453, mediated by JAK2/oestrogen-related receptor-α signalling and the induction of mitochondrial apoptosis pathways." (PMID 32493972, 2020). "JAK2 inhibitors cooperate with SMO inhibitors to inhibit the growth and metastasis of breast cancer cells." (PMID 33664765, 2020). "ODZ10117 did not significantly inhibit the JAK family of tyrosine kinases, including JAK1, JAK2, JAK3, and TYK2, in breast cancer cells and Hodgkin’s lymphoma cells." (PMID 31684051, 2019). "Approximately 90% of the primary breast cancers overexpressed HER3, p-mTOR, p-4EBP1, p-JAK2, p-STAT3, and 50% overexpressed p-Paxillin." (PMID 31667338, 2019). "In breast cancer-initiating stem cells, when stimulated by VEGF, VEGFR2 binds to JAK2 and activates STAT3, and maintains cell self-renewal by promoting MYC and SOX2 expression and induces sphere formation." (PMID 30819137, 2019).
breast cancer (continued). "While the role of PRL in breast cancer has yet to be fully defined, PRL and its signaling pathway Jak2/Stat5 were shown to stabilize cell adhesion complexes and suppress the EMT process and invasive properties of breast cancer cells." (PMID 30987013, 2019). "(B, C) A combined panel of selected breast cancer and near-normal cell lines was reverse-transfected with 10 nM pooled JAK1, JAK2, STAT3 or KRAS siRNAs and cell viability determined after 6 days." (PMID 30777101, 2019). "Because PAK1 interacts with JAK2, we sought to identify PAK1-interacting proteins in breast cancer cells to determine the molecular function of PAK1." (PMID 31658701, 2019). "By contrast, GRAMD1B expression was down-regulated by the JAK2 inhibitor AG490, suggesting that the JAK/STAT cascade regulates GRAMD1B expression in breast cancer cells." (PMID 29934528, 2018). "Meanwhile, in the C3A human liver cancer cells, MCF-7 breast cancer cells and CFPAC-1 pancreatic cancer cells treated by MR-409, there was also a dramatic decrease in phosphorylation of GHR/JAK2/STAT5." (PMID 29983893, 2018). "TFRG also markedly reduced tumor mass of breast cancer cell MDA-MB-231 xenografts with suppression of iNOS expression, formation of 3-nitrotyrosine (3-NT), and inactivation of protumorigenic JAK2/STAT3 signaling pathway." (PMID 29951107, 2018). "JAK2/STAT3 signaling was also reported to be involved in GPER signaling in the hypothalamus and SKBR-3 breast cancer cells." (PMID 28301550, 2017). "Taken together, these results demonstrated that dimerization of EGFR and HER2 activates the JAK2/STAT1 signaling axis and induces ACTA2 expression in breast cancer cells." (PMID 28881584, 2017). "Taken together, these results demonstrated that induction of ACTA2 by EGFR and HER2 dimerization was regulated through a JAK2/STAT1 signaling pathway, and aberrant ACTA2 expression accelerated the invasiveness and metastasis of breast cancer cells." (PMID 28881584, 2017). "Taken together, our results suggest that TA modulates EGF‐R/Jak2/STAT1/3 and P38/STAT1/p21Waf1/Cip1 pathways and induce G1‐arrest and intrinsic apoptosis in breast carcinomas." (PMID 27862996, 2017). "In MCF-7 and SKBR3 breast cancer cells, pre-treatment with a LDFI-leptin receptor antagonist abrogated the leptin activation of Jak2, Stat3, Akt and ERK1/2 proteins." (PMID 27480179, 2016). "In a three-dimensional collagen-I environment, we reported that increased stiffness/collagen density increases PRL signals to the FAK/SFK/ERK1/2 cascade in ERα+ breast cancer cells, while decreasing PRL signals to JAK2/STAT5." (PMID 27344177, 2016). "In melanoma and breast cancer, CD276 has been reported to promote metastasis and chemoresistance through regulating JAK2/STAT3 signaling pathways and promoting the expression of cytokines and other metastasis-associated genes." (PMID 27329595, 2016). "IL-1 upregulation involves leptin activation of JAK2/STAT, PKC, p38, MAPK/ERK1/2, PI-3K/AKT1 and JNK suggesting that multiple leptin-induced signaling pathways can affect leptin-IL-1 crosstalk in breast cancer." (PMID 27472371, 2016). "Our lab has previously demonstrated that PRL-activated tyrosine kinase JAK2 phosphorylates PAK1 on tyrosines 153, 201, and 285, and that tyrosyl phosphorylated PAK1 (pTyr-PAK1) augments migration and invasion of breast cancer cells." (PMID 27542844, 2016). "Among the plethora of kinase receptors that stimulate STATs, janus kinases (JAK), in particular JAK2 driving STAT3 and STAT5 activation, have been reported to have significant roles in breast cancer." (PMID 27406745, 2016). "Knock down of both JAK1 and JAK2 enhanced the lethality of lapatinib and of afatinib in the BT474 and SUM149 mammary carcinoma cells." (PMID 27379204, 2016). "Most physiological PRL actions on the mammary gland are mediated through the JAK2/STAT5 pathway, and in breast cancer, activated STAT5 predicts sensitivity to estrogen targeted therapies and favorable clinical outcomes." (PMID 25607819, 2015).